CSRP3 (cysteine and glycine rich protein 3)
Description:
Positive regulator of myogenesis. Acts as a cofactor for myogenic bHLH transcription factors such as MYOD1, and probably MYOG and MYF6. Enhances the DNA-binding activity of the MYOD1:TCF3 isoform E47 complex and may promote formation of a functional MYOD1:TCF3 isoform E47:MEF2A complex involved in myogenesis (By similarity). Plays a crucial and specific role in the organization of cytosolic structures in cardiomyocytes. Could play a role in mechanical stretch sensing. May be a scaffold protein that promotes the assembly of interacting proteins at Z-line structures. It is essential for calcineurin anchorage to the Z line. Required for stress-induced calcineurin-NFAT activation (By similarity). The role in regulation of cytoskeleton dynamics by association with CFL2 is reported conflictingly: Shown to enhance CFL2-mediated F-actin depolymerization dependent on the CSRP3:CFL2 molecular ratio, and also shown to reduce the ability of CLF1 and CFL2 to enhance actin depolymerization. Proposed to contribute to the maintenance of muscle cell integrity through an actin-based mechanism. Can directly bind to actin filaments, cross-link actin filaments into bundles without polarity selectivity and protect them from dilution- and cofilin-mediated depolymerization; the function seems to involve its self-association. In vitro can inhibit PKC/PRKCA activity. Proposed to be involved in cardiac stress signaling by down-regulating excessive PKC/PRKCA signaling (By similarity). [Isoform 2]: May play a role in early sarcomere organization. Overexpression in myotubes negatively regulates myotube differentiation. By association with isoform 1 and thus changing the CSRP3 isoform 1:CFL2 stoichiometry is proposed to down-regulate CFL2-mediated F-actin depolymerization.
Synonyms: CRP3; CLP; MLP; CMD1M; CMH12
Tractability: PROTAC: ubiquitination databases record sites on it.
Gene: Protein-coding gene on chromosome 11 (19,176,519 to 19,210,571, reverse strand). Ensembl gene ENSG00000129170.
Subcellular location: Nucleus; Cytoplasm; Cytoplasm, cytoskeleton; Cytoplasm, myofibril, sarcomere, Z line; Cytoplasm, myofibril, sarcomere; Cytoplasm, myofibril, sarcomere, Z line (Isoform 2)
Subcellular location (Human Protein Atlas): Cytosol; Nucleoplasm
Gene Ontology:
Molecular function: identical protein binding; protein binding; structural constituent of muscle; telethonin binding; actinin binding
Biological process: cardiac muscle contraction; cardiac muscle hypertrophy; detection of muscle stretch; establishment of protein localization to organelle; positive regulation of transcription by RNA polymerase II; sarcomere organization; cardiac muscle tissue development; cardiac myofibril assembly; intracellular calcium ion homeostasis; muscle tissue development; regulation of the force of heart contraction; skeletal muscle tissue development
Cellular component: cytosol; Z disc; cytoplasm; nucleus; cytoskeleton; sarcomere
Genetic constraint (gnomAD): Loss-of-function variants: 22 observed, 24.03 expected, observed/expected ratio (o/e) 0.92, 90% interval 0.65 to 1.31. The upper end of that interval is the gene's LOEUF score, 1.31, which puts it in group 5 of 6, group 1 being the genes least tolerant of losing a copy. Missense variants: 238 observed, 258.51 expected, observed/expected ratio (o/e) 0.92, 90% interval 0.83 to 1.02. Synonymous variants: 103 observed, 97.77 expected, observed/expected ratio (o/e) 1.05, 90% interval 0.9 to 1.24.
Gene-disease validity (ClinGen):
ClinGen rates the evidence that CSRP3 causes each of these diseases.
hypertrophic cardiomyopathy (semidominant): Definitive. A condition in which the myocardium is hypertrophied without an obvious cause.
dilated cardiomyopathy 1M (autosomal dominant): Limited. Any familial isolated dilated cardiomyopathy in which the cause of the disease is a mutation in the CSRP3 gene.
Homologues: Orthologues: chimpanzee CSRP3 (99% identical), dog CSRP3 (99% identical), rabbit CSRP3 (99% identical), guinea pig CSRP3 (98% identical), mouse Csrp3 (98% identical), pig CSRP3 (96% identical), rat Csrp3 (96% identical), tropical clawed frog csrp3 (79% identical), macaque CSRP3 (75% identical), zebrafish csrp3 (74% identical), Drosophila melanogaster Mlp60A (49% identical), Drosophila melanogaster Mlp84B (46% identical), and 1 more. Paralogues in human: CSRP1 (66% identical), CSRP2 (66% identical).